THEMIS2 (thymocyte selection associated family member 2)
Description:
May constitute a control point in macrophage inflammatory response, promoting LPS-induced TLR4-mediated TNF production. Determines the threshold for activation of B cells by low-affinity and low-avidity ligands via PLCG2 activation and its downstream pathways (By similarity).
Synonyms: C1orf38; ICB1; ICB-1
Tractability: PROTAC: ubiquitination databases record sites on it; its protein half-life has been measured.
Gene: Protein-coding gene on chromosome 1 (27,872,543 to 27,886,685, forward strand). Ensembl gene ENSG00000130775.
Subcellular location: Nucleus; Cytoplasm
Subcellular location (Human Protein Atlas): Nucleoplasm
Gene Ontology:
Molecular function: protein binding
Biological process: cell adhesion; regulation of B cell activation; T cell receptor signaling pathway
Cellular component: cytoplasm; nucleus
Genetic constraint (gnomAD): Loss-of-function variants: 30 observed, 48.64 expected, observed/expected ratio (o/e) 0.62, 90% interval 0.46 to 0.84. The upper end of that interval is the gene's LOEUF score, 0.84, which puts it in group 3 of 6, group 1 being the genes least tolerant of losing a copy. Missense variants: 698 observed, 842.8 expected, observed/expected ratio (o/e) 0.83, 90% interval 0.78 to 0.88. Synonymous variants: 335 observed, 354.44 expected, observed/expected ratio (o/e) 0.95, 90% interval 0.86 to 1.03.
Homologues: Orthologues: chimpanzee THEMIS2 (99% identical), macaque THEMIS2 (94% identical), dog THEMIS2 (72% identical), guinea pig THEMIS2 (71% identical), rabbit THEMIS2 (70% identical), rat Themis2 (69% identical), mouse Themis2 (69% identical), pig THEMIS2 (65% identical), zebrafish themis2 (34% identical), tropical clawed frog themis2 (32% identical). Paralogues in human: THEMIS (31% identical).